NUSAP1 (nucleolar and spindle associated protein 1)
Diseases named in the same sentence as NUSAP1 in open-access papers (continued):
Sharing a sentence is not in itself a finding about the gene and the disease.
glioma (continued). "Some studies have shown overexpression of NUSAP1 in renal cell carcinoma, colon cancer, glioma, and other malignant tumors and its significant association with tumor invasion and metastasis, as well as with a poor prognosis in patients." (PMID 32420375, 2020). "To summarize, NUSAP1 was overexpressed in glioma patients in a grade-dependent manner compared with normal brains." (PMID 32317623, 2020). "In comparison with that in the normal brain control, the level of NUSAP1 was upregulated in 12 glioma and GBM data sets, not only in patients but also in cell lines." (PMID 32317623, 2020). "NUSAP1 has been reported as a potential prognostic marker for patients with glioma, and knockdown of NUSAP1 suppressed the proliferation of glioma cells by inducing G2/M phase cell cycle arrest and apoptosis." (PMID 30678687, 2019). "Previous study shows that NUSAP1 expression is correlated not only with glioma grade but also with prognosis of glioma patients." (PMID 30356407, 2018). "Taken together, NUSAP1 protein upregulation in glioma contributes to glioma progression and correlates with poor prognosis of the disease." (PMID 28899410, 2017). "In gliomas, NUSAP1’s role is becoming increasingly clear, with early studies suggesting that its elevated expression in glioma cells may drive malignant behaviors, such as invasiveness and resistance to apoptosis." (PMID 39975552, 2025). "Therefore, the suppression of NUSAP1 showed inhibitory effects on both glioma cell proliferation and migration, which were further validated using the CCK-8 assay." (PMID 39975552, 2025). "DNA methyltransferase's mRNA expression was markedly reduced when NUSAP1 was silenced, but not the expression of an oncogene linked to gliomas." (PMID 39911278, 2025). "Both in vitro and in vivo assays—such as colony formation, scratch wound healing, transwell migration, and flow cytometry—demonstrated that NUSAP1 silencing significantly suppressed malignant behaviors of glioma cells and induced a marked increase in apoptosis." (PMID 39975552, 2025). "In-depth exploration of NUSAP1’s mechanisms in glioblastoma could enhance our understanding of its response to immunotherapy, suggesting that targeting NUSAP1 may offer therapeutic benefits for glioma patients." (PMID 39975552, 2025). "This gap in research highlights the need for further investigation into how NUSAP1 may contribute to immune suppression and treatment resistance in gliomas." (PMID 39975552, 2025). "Furthermore, elevated NUSAP1 levels indicate a diminished overall survival (OS) expectation among glioma patients." (PMID 39975552, 2025). "In addition, data from the TCGA also showed NUSAP1 mRNA expression levels significantly increased with higher WHO grade of glioma." (PMID 36982952, 2023). "All these findings suggest that LINC01393 might be served as a miR-128-3p sponge to promote the progression of glioma via upregulating NUSAP1." (PMID 36982952, 2023). "Moreover, higher NUSAP1 expression indicated worse prognosis of glioma from TCGA (HR = 4.45, 95% CI = 3.35 to 5.91, p < 0.001), and its prognostic role was validated by GSE4412 using PrognoScan (p = 0.001303)." (PMID 36982952, 2023). "Importantly, previous studies reported that AIFM3, LDHD, LYNX1, SCN2B or TMEM56 were all negatively corelated with glioma, and GINS1, KIFC1, NUF2, NUSAP1 or TPX2 were both positively related to glioma progression." (PMID 33277782, 2021). "NUSAP1 was expressed in a grade-dependent manner in glioma patients." (PMID 32317623, 2020). "According to these results, NUSAP1 expression increased significantly even in grade I glioma." (PMID 32317623, 2020). "NUSAP1 was highly expressed in glioma and GBM samples in a grade-dependent manner." (PMID 32317623, 2020). "Furthermore, the level of NUSAP1 was enhanced in dead patients who had been diagnosed with glioma, and patients with high expression of NUSAP1 showed lower survival." (PMID 32317623, 2020).
glioma (continued). "Knockdown of NUSAP1 expressing suppress glioma cells growth and promote glioma cell apoptosis." (PMID 30356407, 2018). "Moreover, univariate and multivariate survival analyses revealed that NUSAP1 expression was an independent prognostic factor of glioma (P < 0.001) similar to the WHO grade (P < 0.001)." (PMID 28899410, 2017). "Importantly, the simulative effect of SMO agonist purmorphamine on GLI1 activity in U-87 MG glioma cells was dramatically arrogated by NUSAP1 depletion." (PMID 28899410, 2017). "Understanding the role of NUSAP1 in these processes could open new avenues for developing targeted therapies aimed at improving the efficacy of immunotherapy and overcoming drug resistance in glioma patients." (PMID 39975552, 2025). "Despite its emerging significance, the relationship between NUSAP1 and critical processes in cancer immunology and oncology, such as molecular mechanisms of immune regulation, immunotherapeutic responsiveness, and drug sensitivity, remains largely unexplored in gliomas." (PMID 39975552, 2025). "Additionally, research into NUSAP1 as a potential therapeutic target is growing, indicating that modulating its expression and function could provide new treatment options for gliomas." (PMID 39975552, 2025). "Notably, the C2 NUSAP1+ glioma cell subpopulation was exclusive to the IDH1 wildtype group." (PMID 39975552, 2025). "In addition, high expression of NUSAP1 indicated poor prognosis in three glioma data sets." (PMID 32317623, 2020). "Moreover, we found that, in response to SMO agonist purmorphamine treatment, the activity of GLI1 was only slightly increased in SW 1088 glioma cells, which displays low NUSAP1 expression, but significantly increased in U-87 MG glioma cells, which exhibits high NUSAP1 expression." (PMID 28899410, 2017). "Based on inferred copy number variations (CNV), cells with elevated CNV levels were classified as glioma cells revealing three subpopulations: C0 MALAT1+ glioma cells, C1 AKAP9+ glioma cells, and C2 NUSAP1+ glioma cells." (PMID 39975552, 2025). "In glioma, the long non-coding RNA LINC01393 promotes the malignant biological behavior of tumors by regulating the miR-128-3p/NUSAP1 axis." (PMID 38441732, 2024). "Four different glioma cell lines were utilized to address the assumed roles of LINC01393, miR-128-3p and NUSAP1 signaling in the regulation of GBM cells progression." (PMID 36982952, 2023). "GSEA based on NUSAP1 and LINC01393 expression in the TCGA LGG-GBM database was performed to explore the potential molecular pathways in gliomas." (PMID 36982952, 2023). "NUSAP1 mRNA expression was significantly higher in multiple glioma types (AA, AO, OD, and GBM) than normal brain tissue in seven glioma datasets of Oncomine as well as in the merged GTEx and TCGA LGG-GBM datasets." (PMID 36982952, 2023). "Apart from the B2M was abnormally upregulated, other recent reported molecules such as NUSAP1, Paxillin, CAVIN1, and PARP9 also overexpressed in glioma tissues." (PMID 33960680, 2021). "Subsequently, colony formation assays were performed on U251 and LN229 glioma cell lines in both the negative control (NC) and si-NUSAP1 experimental groups." (PMID 39975552, 2025). "Although NUSAP1 has not been extensively studied in the context of glioma immunology, its potential involvement in immune evasion and treatment sensitivity presents a promising area for exploration." (PMID 39975552, 2025). "Notably, we identified three major glioma cell subpopulations (C0 MALAT1+, C1 AKAP9+, and C2 NUSAP1+), which were highly correlated with tumor malignancy." (PMID 39975552, 2025). "In the present study, according to ceRNA theory, we first predicted the potential upstream RNAs of NUSAP1 by multiple public databases and then identified lncRNA LINC01393 as a carcinogenic factor promoting glioma progression via potentially inhibit effect of miR-128-3p." (PMID 36982952, 2023).
glioma (continued). "NUSAP1 enhances ATR stability by promoting its sumoylation and inhibiting its ubiquitin-dependent degradation, thereby promoting resistance to temozolomide and doxorubicin in glioma." (PMID 37349788, 2023). "Although researchers have identified various proliferation-associated biomarkers as prognostic indicators for glioma patients, such as Par6, chromobox protein homolog 3 (CBX3) and nucleolar and spindle-associated protein 1 (NUSAP1), none of them has been routinely applied in clinical practice." (PMID 33712571, 2021).
prostate carcinoma (23 papers, 2013 to 2024). A carcinoma that arises from epithelial cells of the prostate gland. "Since genomic rearrangements have been observed in prostate cancers, we sought to investigate further the interactions of these R-loop-associated proteins and NUSAP1 in prostate cancer cells." (PMID 37047232, 2023). "Elevated NUSAP1 expression is associated with increased aggressiveness and poor patient outcome in prostate cancer." (PMID 28404898, 2017). "We previously found that NUSAP1 is overexpressed in recurrent prostate cancer and is regulated, at least in part, by loss of RB1 via the RB1/E2F1 axis." (PMID 28404898, 2017). "We have previously identified nucleolar and spindle associated protein 1 (NUSAP1) as a prognostic biomarker in early stage prostate cancer." (PMID 28404898, 2017). "Increased expression of nucleolar and spindle-associated protein 1 (NUSAP1) has been identified as a robust clinical biomarker of aggressive prostate cancer and is part of two commercial prognostic gene expression panels used to analyze prostate tissue samples." (PMID 37047232, 2023). "NUSAP1 was linked with proliferation and invasion of prostate cancer cells, but this gene might be responsible for proliferation and invasion of pituitary prolactinoma cells." (PMID 33709028, 2021). "Furthermore, NUSAP1 overexpression is associated with deterioration in melanoma and breast and prostate cancers." (PMID 34094915, 2021). "The expression of RRM2 and NUSAP1 in prostate cancer patients was further verified in PRAD_TCGA datasets." (PMID 37596700, 2023). "Taken together, our results suggested that RRM2 and NUSAP1 were not only correlated with poor prognosis of PCa patients but also very likely to contribute to the progression of prostate cancer." (PMID 37596700, 2023). "First, at the beginning of the study, our analysis revealed RRM2 and NUSAP1 to be strong predictors of prostate cancer, and we believe that NUSAP1 is another interesting gene that is worth investigating." (PMID 37596700, 2023). "To confirm the interaction of NUSAP1 and ILF2, DHX9, and HNRPC, we transiently transfected LNCaP and DU145 prostate cancer cell lines with empty vector or Flag-NUSAP1." (PMID 37047232, 2023). "To identify candidate interacting proteins, we performed affinity purification–mass spectrometry (AP–MS) and validation of candidate binding partners to identify a novel role for NUSAP1 in the regulation of R-loops and DNA damage in prostate cancer." (PMID 37047232, 2023). "Elevated NUSAP1 expression increases cell motility and invasion in prostate cancer and astrocytoma cells and metastasis in xenograft models." (PMID 37047232, 2023). "NUSAP1 expression is increased by E2F1, and allelic loss of the retinoblastoma gene, a common finding in prostate cancer, can also increase NUSAP1 expression." (PMID 37047232, 2023). "Increased expression of NUSAP1 has been identified as a robust prognostic biomarker in prostate cancer and other malignancies." (PMID 37047232, 2023). "In recent years, studies have reported that NUSAP1 was involved in malignant pleural mesothelioma (MPM), liver cancer, prostate cancer, and other cancers, with diagnostic value." (PMID 35710427, 2022). "NuSAP1 is a microtubule-binding protein involved in several types of cancers such as prostate cancer, colorectal cancer, and astrocytoma." (PMID 32651974, 2021). "Recent studies have found that NuSAP1 was overexpressed in several types of cancers such as prostate cancer, colorectal cancer, and astrocytoma." (PMID 32651974, 2021). "For instance, NUSAP1 is highly overexpressed in colon and prostate cancers and closely correlated with poor prognosis." (PMID 33489890, 2020). "Studies show that NUSAP1 is involved in human malignancies, including pancreatic adenocarcinoma, glioblastoma, hepatocellular carcinoma, prostate cancer, etc." (PMID 33489890, 2020).
prostate carcinoma (continued). "Overexpression of NUSAP1 correlates with poor survival in melanoma, cervical carcinoma, prostate cancer and glioblastoma multiforme." (PMID 32081836, 2020). "Previous studies showed that NUSAP1 is upregulated in several cancers, including prostate cancer, colorectal cancer, and astrocytoma." (PMID 30678687, 2019). "Loss of RB1 is common in prostate cancer, controls progression into castration-resistant prostate cancer, and is a mechanism responsible for overexpression of NUSAP1." (PMID 28404898, 2017). "NUSAP1 is a highly validated biomarker of prostate cancer progression and overexpressed in multiple cancer types." (PMID 28404898, 2017). "Our findings provide insights into the importance of NUSAP1 in prostate cancer progression and provide a rationale for further study of NUSAP1 function, regulation, and clinical utility." (PMID 28404898, 2017). "While NUSAP1 has been linked to proliferation based on its role in assembly of the mitotic spindle, our results provide compelling evidence that NUSAP1 plays a direct role in driving prostate cancer progression." (PMID 28404898, 2017). "Our analyses of prostate cancer cell lines and prostate cancer patient samples suggest that NUSAP1 is more than just a prognostic biomarker in prostate cancer, but actually plays a role in driving prostate cancer progression." (PMID 28404898, 2017). "To better understand the role of NUSAP1 in prostate cancer progression, we tested the effects of increased and decreased NUSAP1 expression in cell lines, in vivo models, and patient samples." (PMID 28404898, 2017). "Modest NUSAP1 overexpression in prostate cancer xenografts, comparable to levels observed in human prostate cancers, significantly increased metastases and modestly affected tumor volume." (PMID 28404898, 2017). "High expression of NUSAP1 has been observed in several types of tumors, such as pancreatic adenocarcinoma, acute myeloid leukemia and prostate cancer." (PMID 28899410, 2017). "To better understand the functional role of NUSAP1 in prostate cancer, we explored the effects of overexpression and knockdown of NUSAP1 in in vitro and in vivo models." (PMID 28404898, 2017). "For example, MYBPC1, UBE2C and NUSAP1 have been previously reported to be differentially expressed throughout prostate cancer progression." (PMID 23826159, 2013). "Notably, down-regulation of NUSAP1 expression has been observed to inhibit migration, proliferation, and invasion of renal cancer cells, whereas high expression of NUSAP1 has been found to promote the growth and invasion of prostate cancer cells." (PMID 38441732, 2024). "Additionally, we identified five downstream genes (IGF1R, BMI1, RHAMM, NuSAP1, and PBK) of E2F1 in prostate cancer, and these genes are associated with the survival and proliferation of prostate cancer." (PMID 38374143, 2024). "To determine whether NUSAP1, ILF2, DHX9, and HNRPC are associated with R-loops in prostate cancer cells, we performed immunoprecipitation using the S9.6 antibody in LNCaP cells." (PMID 37047232, 2023). "Therefore, human localized prostate cancer samples show co-expression of NUSAP1 with its binding partners, ILF2 and DHX9." (PMID 37047232, 2023). "E2F1 might regulate NUSAP1 expression in recurrent prostate cancer through binding CCAAT box in promoter region of NUSAP1." (PMID 36982952, 2023). "In prostate cancer, NUSAP1 increases invasion, cell migration, and metastasis." (PMID 37047232, 2023). "Moreover, overexpression of NUSAP1 enhanced the progression and invasion of astrocytoma and prostate cancer cells." (PMID 30678687, 2019). "Moreover, it was found that NUSAP1 promotes the invasion, migration, and metastasis of prostate cancer cells by regulating FAM101B which is regarded as a TGFβ1 signaling effector related to epithelial to mesenchymal transition (EMT)." (PMID 31729978, 2019).
prostate carcinoma (continued). "NUSAP1 expression is regulated by E2F transcription factor 1 (E2F1) and by loss of retinoblastoma-associated protein 1 (RB1), an important molecular pathway that becomes altered in aggressive forms of prostate cancer." (PMID 28404898, 2017). "Moreover, NUSAP1 promoted prostate cancer progression by increasing the proliferation and invasion of prostate cancer cells." (PMID 28899410, 2017). "Since knockdown of NUSAP1 results in reduced invasion of PC-3 prostate cancer cells, we hypothesized that overexpression of NUSAP1 might have the opposite effect, leading to increased invasion of prostate cancer cells." (PMID 28404898, 2017). "Since FAM101B is involved in pathways involved in cancer cell invasion and metastasis, we wondered if FAM101B might play a role downstream of NUSAP1 in making prostate cancer cells more aggressive." (PMID 28404898, 2017). "However, since modest increases in expression were achieved and tolerated in our prostate cancer cell lines, we were able to demonstrate that increased NUSAP1 expression increases invasion and migration in vitro, and metastasis in vivo." (PMID 28404898, 2017). "Furthermore, elevated expression level of NUSAP1 may increase proliferation and invasion of PCa cells, positively affecting prostate cancer progression." (PMID 36258196, 2022). "Analysis of NUSAP1, ILF2, and DHX9 in the TCGA dataset parallels our findings, substantiating the important role of the NUSAP1 and ILF2 interaction in prostate cancer aggressiveness." (PMID 37047232, 2023). "Overexpression of NUSAP1 or EGFP control in DU145, LNCaP, PC-3, or 22Rv1 prostate cancer cell lines using a lentiviral vector did not significantly affect proliferation rates over a period of 5 days." (PMID 28404898, 2017). "NUSAP1 has also been shown to participate in epithelial-mesenchymal transition by regulating FAM101B, an effector molecule of the TGFβ1 signaling pathway, thus promoting the invasion, migration, and metastasis of prostate cancer." (PMID 38441732, 2024). "In prostate cancer cell lines in vitro, overexpression of NUSAP1 did not increase proliferation, but did increase invasion and migration, and depletion of NUSAP1 decreased proliferation, invasion, and migration." (PMID 28404898, 2017). "However, forced overexpression of NUSAP1 does not affect prostate cancer cell growth in vitro or in vivo." (PMID 37047232, 2023). "One gene consistently modulated, FAM101B, correlates with NUSAP1 expression in patient samples and appears to be an important downstream effector of NUSAP1 in tumor progression since knockdown of FAM101B abolished NUSAP1's effects on prostate cancer cell invasion and migration." (PMID 28404898, 2017). "NUSAP1 binds DNA to the mitotic spindle and we have shown that knockdown of NUSAP1 results in reduced proliferation of DU145, LNCaP, PC-3, and PC-3-RB1 low prostate cancer cells grown in culture, yet it was unknown whether NUSAP1 overexpression would enhance proliferation." (PMID 28404898, 2017).